BDNF (brain derived neurotrophic factor)
Diseases named in the same sentence as BDNF in open-access papers (continued):
Sharing a sentence is not in itself a finding about the gene and the disease.
coronary artery disease (42 papers, 2010 to 2026). "While platelet hyperactivity is generally deleterious in coronary artery disease and is associated with poorer cognitive outcomes, platelets also release large amounts of BDNF during activation." (PMID 39568824, 2024). "Studies have found that patients with coronary artery disease exhibited significantly lower plasma BDNF, and the serum BDNF levels were associated with an increased risk of adverse cardiovascular events and death." (PMID 35906216, 2022). "SNP rs6265 was found to be associated with BDNF concentrations and coronary artery disease in the FHS." (PMID 34827728, 2021). "In contrast, a second cross-sectional study (n = 88) reported a positive association between CRF and BDNF in older, largely sedentary patients with coronary artery disease (mean age: 63 years, 85% male)." (PMID 31635145, 2019). "Circulating levels of Brain Derived Neurotrophic Factor (BDNF) are lower in coronary heart disease (CHD) than in healthy subjects and are associated with coronary events and mortality." (PMID 30674980, 2019). "High serum sVCAM-1 associates with coronary artery disease as well as lower brain-derived neurotrophic factor values during oral glucose tolerance test." (PMID 28646244, 2017). "Consistent with this idea, high levels of BDNF were associated with cardiopulmonary fitness in patients with coronary artery disease." (PMID 26161003, 2015). "Beyond its well-documented roles, the BDNF Val66Met polymorphism has also been implicated in a range of cardiovascular diseases, inclusive of cardiometabolic disorders, coronary artery disease (CAD), and cardiomyopathy associated with Duchenne muscular dystrophy (DMD)." (PMID 38988887, 2024). "There is a close association between BDNF and coronary heart disease." (PMID 38707889, 2024). "Moreover, ischemic heart disease and endothelial dysfunction are associated with a reduction in brain-derived neurotrophic factor (BDNF), which supports the functions and survival of neurons." (PMID 38275390, 2023). "Low BDNF levels have been frequently observed in patients with coronary artery disease and heart failure (HF) and have been associated with HF severity and unfavourable outcome in HF patients, whereas higher serum BDNF levels have been associated with a lower risk of CVD and mortality." (PMID 37895349, 2023). "In approximately 30% of the general population, BDNF harbors a nonsynonymous single nucleotide polymorphism that may be associated with cardiometabolic disorders, coronary artery disease, and Duchenne muscular dystrophy cardiomyopathy." (PMID 34210092, 2021). "Relating serum BDNF levels with two-dimensional echocardiographic indices will provide insights into the BDNF mediated pathophysiology in coronary artery disease (CAD) that may shed light upon potential diagnostic biomarkers." (PMID 33004884, 2020). "Interestingly, modifications of BDNF gene, including rs10767664 and rs 6265 polymorphisms, are associated with coronary artery disease and myocardial infarction." (PMID 30674980, 2019). "The combined impact of cortisol and BDNF levels associated with silent ischaemia may increase future coronary artery disease risk via compensatory increases in blood pressure." (PMID 27966001, 2016). "Although the exact nature of the relationship between BDNF and heart disease is unknown, several studies have suggested that increased BDNF levels are associated with risks for coronary heart disease." (PMID 20404913, 2010). "Thus, reduced BDNF secretion due to brain hypoplasia, which in turn leads to altered cardiovascular homeostasis, may be one of the pathogenic mechanisms of coronary heart disease." (PMID 38707889, 2024). "Clinical studies have found reduced plasma BDNF concentrations in patients with coronary artery disease." (PMID 38707889, 2024).
coronary artery disease (continued). "In addition, BDNF is involved in substance metabolism and plays a role in the control of coronary heart disease risk factors.BDNF is involved in lipid metabolism and may regulate atherosclerotic plaque formation as well as vascular endothelial inflammatory processes." (PMID 38707889, 2024). "A comparative study investigated the association between BDNF and therenin enzyme before and after percutaneous coronary intervention (PCI), and therole of this enzyme in patients with coronary heart disease (CHD)." (PMID 39077334, 2024). "Thus, if, on the one hand, it is clear that BDNF contributes to the pathophysiology of coronary artery disease and has therefore been proposed as a potential diagnostic tool, an elevated BDNF level may, on the other hand, represent a compensatory response to the heart and vessels on injury." (PMID 37895349, 2023). "In another study, the difference in BDNF levels between the coronary sinus and aorta was significantly greater in the unstable angina group compared with the stable angina and non-coronary artery disease groups." (PMID 38145212, 2023). "Lower BDNF levels were confirmed in ischemic heart disease in both subgroups (serum: SMD = −0.73, 95% CI: −1.84; 0.37, p-value = 0.192; plasma: SMD: −0.37, 95% CI: −0.67; −0.08, p-value = 0.013)." (PMID 38137853, 2023). "It has been reported that the level of circulating BDNF decreased in angina and coronary artery disease." (PMID 35906216, 2022). "Based on this, this study aimed to explore the expression of serum SAH, IL-1β, Hcy, TNF-α, BDNF in coronary heart disease and the relationship with the degree of coronary artery disease." (PMID 35282820, 2022). "The findings of this study did not reveal an association of accelerometer-measured PA and SB pattern variables with serum BDNF in individuals with coronary heart disease." (PMID 36385629, 2022). "Patients with coronary artery disease exhibited significantly lower plasma BDNF levels than those of control patients." (PMID 35439934, 2022). "This is the first study to analyze the association of accelerometer-measured patterns of habitual physical activity (PA) and sedentary behavior (SB) with serum BDNF in individuals with coronary heart disease." (PMID 36385629, 2022). "Based on the findings of the present study, the levels of SAH, IL-1β, Hcy, TNF-α and BDNF can predict the severity of coronary heart disease." (PMID 35282820, 2022). "BDNF in serum of patients with coronary heart disease can be used as an effective biological indicator to monitor the degree of coronary heart disease and severity of coronary stenosis." (PMID 35439934, 2022). "Recently, a new study also uncovered serum BDNF was differentially expressed in plaque tissues in patients with coronary heart disease compared with normal intimae in healthy subjects using microarray profiling analysis and qRT-PCR validation." (PMID 33477900, 2021). "In patients with ischemic heart disease or acute coronary syndrome, BDNF levels are significantly lower compared to healthy controls." (PMID 31659205, 2019). "Moreover, low serum BDNF levels in patients with coronary artery disease (CAD) were associated with an increased risk of adverse cardiovascular events and mortality." (PMID 29409455, 2018). "Circulating brain-derived neurotrophic factor (BDNF) predicts survival rate in patients with coronary artery disease (CAD)." (PMID 30424498, 2018). "The reduction of BDNF levels can affect the metabolism of related substances, leading to the emergence of obesity, elevated blood glucose, etc., and adversely affecting patients with coronary heart disease." (PMID 38707889, 2024). "For example, a positive association between symbol digit coding (i.e., processing speed) and BDNF was reported in Canadian patients with coronary artery disease, and notably, poorer performance on the symbol digit coding has been associated with increased risk of vascular diseases." (PMID 36092801, 2022).
coronary artery disease (continued). "However, there are few studies on the expression of serum SAH, IL-1β, Hcy, TNF-α, and BDNF in coronary heart disease and their relationship with the extent of coronary artery stenosis." (PMID 35282820, 2022). "Therefore, several attempts have been made to use circulating BDNF as a biomarker for the diagnosis and severity of cardiovascular diseases, mainly focused on coronary artery disease." (PMID 36078878, 2022). "We also performed ELISA to investigate the corresponding proteins levels of selected genes and showed that serum levels of SPP1, CD36, ATP6V0D2, CHI3L1, MYH11, and BDNF were differentially expressed in patients with coronary heart disease compared with healthy subjects." (PMID 31682178, 2019). "The prevalence of coronary artery disease (CAD) at the baseline (67.8% vs. 57.0%, p = 0.028) was significantly higher in the low BDNF group than in the high BDNF group." (PMID 32679912, 2020). "In the present study, the prevalence of these factors was similar among Low, Middle and High BDNF groups, as well as SMI, left ventricular ejection fraction, and the prevalence of heart failure, coronary artery disease, other cardiovascular diseases, the comorbidities, and medications." (PMID 38319936, 2024). "Additionally, research has shown a negative correlation between Th2 cells and serum BDNF in coronary heart disease patients." (PMID 40124544, 2025). "BDNF levels, but not NT-3, in the unstable angina group had significantly greater differences between the coronary sinus and aorta than those in the stable effort angina or non-coronary artery disease groups." (PMID 34827728, 2021).
amyloid (40 papers, 2013 to 2026). "The BDNF pathway has been consistently linked to core pathological features of amyloidosis and tauopathies because this trophic factor is able to regulate the production and the neurotoxic effects of amyloid b42 and Tau protein hyperphosphorylation." (PMID 24024214, 2013). "Pro-BDNF levels are significantly associated with both amyloid load and pTau in the hippocampus." (PMID 35743271, 2022). "Lower plasma BDNF levels correlate with increased amyloid deposition and greater medial temporal lobe atrophy, indicating its potential as a biomarker for early AD detection." (PMID 40709526, 2025). "BDNF and other neurotrophins have been shown to counteract the damaging action of inflammation and oxidative stress in AD neurons and to decrease amyloid plaque formation." (PMID 40862772, 2025). "Bifidobacterium bifidum BGN4 and Bifidobacterium longum BORI effectively inhibited amyloidosis and apoptotic processes by improving neuroinflammatory responses and BDNF expression and ameliorated cognitive and memory deficits in AD mice." (PMID 37728579, 2024). "First, the reported BDNF downregulation in the literature on Tauopathies and Tau transgenic mouse models is rather a direct consequence of amyloid pathology with the long-term accumulation of Tau." (PMID 38148427, 2024). "The authors reported that consumption of pomegranate peel extract resulted in reduced amyloid plaque density, increased brain-derived neurotrophic factor (BDNF) secretion and decreased acetylcholinesterase (AChE) activity." (PMID 36768185, 2023). "In terms of post-transcription regulation, many miRNAs have been linked to pathways of both diseases, with miR-132 lowering BDNF expression in MDD and tied to both tau and amyloid pathology in LOAD." (PMID 36421693, 2022). "Administration of B. bifidum BGN4 and B. longum BORI effectively suppressed amyloidosis and apoptotic processes and improved synaptic plasticity by ameliorating the neuroinflammatory response and BDNF expression." (PMID 34421576, 2021). "Previous studies indicate that BDNF depletion led to an increase in cortical amyloid plaque numbers and size." (PMID 34194312, 2021). "In summary, intravenous administration of NEP-enhanced hUC-MSCs significantly decreased amyloidosis and neuroinflammation, increased BDNF, NEP, and neurogenesis, and improved cognitive function in an AD mouse model." (PMID 34899919, 2021). "In this regard, we considered BDNF a potential neuroprotectant in amyloidosis-induced neurodegenerative processes." (PMID 32733889, 2020). "The consumption of PPE reduced amyloid plaque density, increased the expression of neurotrophin BDNF and reduced the activity of acetylcholinesterase enzyme." (PMID 27829013, 2016). "Several studies indicate that the cortex and hippocampus, areas of the brain associated with learning and memory, not only exhibit extensive amyloid pathology but also show decreased levels of BDNF in AD." (PMID 25954034, 2015). "We also studied brain BDNF protein levels in APdE9 mice in different ages showing progressive amyloid pathology." (PMID 23844236, 2013). "Preclinical studies have shown that NGF gene delivery can prevent cholinergic degeneration and enhance cognitive performance in rodent and primate models, while BDNF supplementation has been shown to restore synaptic integrity and memory function independently of amyloid clearance." (PMID 40656325, 2025). "MicroRNAs, specifically miR-451a and miR-455-3p, play a regulatory role in neurotrophic factors like brain-derived neurotrophic factor (BDNF), neuroinflammation, and neurotransmitter balance, thereby connecting mild behavioral impairments to amyloid/tau pathology." (PMID 40771197, 2025). "In addition, both hUC-MSCs significantly decreased amyloidosis and neuroinflammation and increased BDNF and neurogenesis, which were induced by stem cell-released EVs." (PMID 34899919, 2021).
amyloid (continued). "Reduction by half in BDNF mRNA, its precursor (proBDNF), and mature BDNF concentration have been detected in the entorhinal, frontal, temporal, and parietal cortex, hippocampus, and basal forebrain of AD brains and in mouse models of amyloid pathology." (PMID 33023629, 2020). "Indeed, when we analyzed the immunohistochemical localization of BDNF in the brains of APdE9 and WT mice, strong anti-BDNF immunoreactivity surrounded amyloid plaques in the hippocampus and cortex of APdE9 mice in a “doughnut-like” fashion." (PMID 23844236, 2013). "As hypothesized before, the observed up-regulation of BDNF synthesis around amyloid plaques of aged APdE9 mice may be an attempt to provide neurotrophic support for degenerating neurons around the plaques." (PMID 23844236, 2013). "In transgenic mice exhibiting amyloidosis, BDNF gene administration post-disease onset reversed synaptic loss, partially normalized abnormal gene expression, enhanced cellular signaling, and restored learning and memory, independent of amyloid plaque load." (PMID 39935805, 2024). "Interestingly, fingolimod was shown to mitigate learning deficits in mice injected with Aβ to mimic AD-like amyloidosis, and this beneficial effect was mediated by increased expression of brain-derived neurotrophic factor (BDNF) and downstream tropomyosin related kinase (TrkB) receptor signaling." (PMID 37014414, 2023). "AD and amyloidosis are known to impair neuronal function and affect brain neurotrophic factors (NGF and BDNF) expression." (PMID 41665021, 2026). "In this regard, compared to the amyloid group, rats that underwent treadmill exercise for 4 weeks in addition to intranasal insulin pretreatment and therapy showed higher levels of IGF1, BDNF, and GLUT4 gene expression in the hypothalamus." (PMID 38987609, 2024). "Similarly, by crossing BDNF+/− mice with APPdE9 mice (bearing APPswe and PSEN1ΔE9 mutations), researchers found that while the haploinsufficiency-induced decrease of BDNF impaired learning and memory, it did not alter amyloid pathology." (PMID 35090576, 2022). "Our study further proved the primary functions of BDNF in neuroprotection and synaptic plasticity against Aβ and tau-induced neurotoxicity, while they had no direct impact on amyloidosis or tau accumulation." (PMID 41480410, 2026). "There was a remarkable amendment in the architecture of the brain and less amyloidosis, together with decreased levels of inflammatory cytokines and upregulation of cAMP, PKA, CREB and BDNF, which may result from the augmented inhibition of PDE4." (PMID 40243772, 2025). "Thus, in the presence of amyloid pathology, GLP-1 analogs seem to stimulate the general energy turnover, the cAMP/PKA/CREB/BDNF pathway and BDNF secretion by astrocytes to evoke BDNF-driven synaptogenesis and neurite outgrowth in neurons." (PMID 36117625, 2022). "While early amyloid burden or GM atrophy has been reported to involve the DMN medial temporal lobe subsystem in the early stage of AD, lower BDNF protein levels in the entorhinal cortex seed region have also been reported implying the vulnerability of this region." (PMID 27494844, 2016). "At first it became apparent that no amyloid plaques could be detected in wildtype and BDNF+/−-mice." (PMID 25852506, 2015). "Consequently, we included it in logistic regression models and discovered its inclusion markedly improved the predictive power of BDNF expression in CD4+ T cells to distinguish between AL amyloidosis patients and myeloma patients without amyloid deposits." (PMID 40977494, 2025).
cognitive disorder (38 papers, 2013 to 2026). A disease affects cognitive processes. "Aging is a major risk factor of cognitive disease, and dysregulation of BDNF/TrkB signaling has been also reported in age-related cognitive disorders." (PMID 35887075, 2022). "In addition, several cognitive diseases have associated deficits in Bdnf expression or BDNF signaling with LTP and memory disturbances." (PMID 27485321, 2016). "By the time a person is diagnosed with a metabolically influenced cognitive disease, previously elevated BDNF levels have dropped significantly." (PMID 36138878, 2022). "On the other hand, the PI3K pathway, which has been demonstrated to be deregulated in several cognitive diseases is also activated by BDNF." (PMID 27485321, 2016). "Interestingly, BDNF regulates VGLUT1 expression during development and hippocampal LTP, and is able to prevent VGLUT1 reduction in cognitive diseases." (PMID 30127717, 2018).